NR5A2 (nuclear receptor subfamily 5 group A member 2)
Diseases named in the same sentence as NR5A2 in open-access papers (continued):
Sharing a sentence is not in itself a finding about the gene and the disease.
cancer (continued). "Mechanistically, NR5A2 and NCOA3 act synergistically to increase Nrf2 expression and inhibit cancer cell ferroptosis." (PMID 39664391, 2024). "The expression of MYC, NR5A2, and SNAI1 was also higher in EC-adjacent tissues than in samples from cancer-free patients." (PMID 36140779, 2022). "The dysregulation of significant cancer-related genes (FAM83H, CXCL12, PITPNA, HMOX1, DGKZ, NR5A2, VMP1, and ID1) was confirmed by qRT-PCR." (PMID 36232920, 2022). "In EC, the expression of cancer-promoting genes, MYC, NR5A2, SNAI1, and TWIST1, was found to be significantly higher in tumor-adjacent tissues than in the matched tumors." (PMID 36140779, 2022). "In cancer cell-free EC-adjacent tissues (TA), the expression of MYC, NR5A2, SNAI1, and CXCR2 was higher than in Ctrl samples." (PMID 36140779, 2022). "Here, we silenced HK2 and NR5A2 alone or in combination in SCC-9 cells and found that knockdown of HK2 or NR5A2 suppressed cancer cell growth." (PMID 34277436, 2021). "VIM positively regulated by NR5A2 affected EMT signaling pathways in metastatic CESC, and naringenin was the inhibitor for the treatment of metastatic CESC via suppressing cancer stemness." (PMID 33842467, 2021). "Liver Receptor Homolog 1 (LRH-1, NR5A2) is an orphan nuclear receptor that is over-expressed in cancers in tissues such as the breast, colon and pancreas." (PMID 22359603, 2012). "Mechanistically, NR5A2 and NCOA3 cooperate to upregulate NRF2, a transcription factor regulating antioxidant gene expression, and inhibiting NR5A2 or NCOA3 enhances BETi’s anti-cancer effects both in vitro and in vivo." (PMID 39867656, 2024). "NR5A2 mRNA expression was also more strongly expressed in normal liver and bile duct, but no change in expression was observed for the respective cancer tissues." (PMID 38012687, 2023). "The expression of MYC, NR5A2, and SNAI1 was found to be higher in EC-adjacent tissues than in samples from cancer-free patients, which shows that tumor-surrounding tissues presented truly elevated expression, not just higher expression than in a tumor because of a decreased tumor expression." (PMID 36140779, 2022). "Since Nr5a2 is a transcriptional co‐activator, it may promote LLC‐SD CSC stem cell like properties and in vivo cancer biology characteristics by transcriptional activation of gene(s) that are regulators of NSCs and CSCs." (PMID 30740909, 2019). "Overexpression of miR-186 also repressed the expression of tumor suppressors, including forkhead box O1 (FOXO1), Nuclear Receptor Subfamily 5 Group A Member 2 (NR5A2), and protein phosphatase, Mg2+/Mn2+ dependent 1B (PPM1B) in endometrial, pancreatic, and bladder cancer cells, respectively." (PMID 29653561, 2018). "The orphan nuclear receptor (NR5A2), which belongs to the NR5A subfamily of nuclear receptors, is expressed in developing and adult tissues of endodermal origin, and can contribute to the development of several cancers through regulating cell proliferation." (PMID 25514243, 2014). "The expression levels of MYC, NR5A2, SNAI1, TWIST1, and STK11 were significantly higher in tumor-adjacent tissues than in the matched EC samples, and this difference was not influenced by the content of cancer cells in cancer-adjacent tissues." (PMID 36140779, 2022).
tumor (38 papers, 2007 to 2026). "In HNSCC tissues, the expression level of NR5A2 was closely associated with the tumor grade; the higher the tumor grade, the higher the expression level of NR5A2." (PMID 38358044, 2024). "Our tumor profiling results underline the importance of customizing treatment to tumors that exhibit the highest combined expression of NR5A2 and SOX2, thereby maximizing the response to therapy." (PMID 38012687, 2023). "Similar results were found among the female patients group and tumor size >5 cm group for the NR5A2 rs3790843 polymorphism in a dominant model." (PMID 25514243, 2014). "We assessed expression of candidate genes at the three risk loci in histologically normal (n = 10) and tumor (n = 8) derived pancreatic tissue samples and observed a marked reduction of NR5A2 expression (chr1q32.1) in the tumors (fold change -7.6, P = 5.7×10−8)." (PMID 27579533, 2016). "Additionally, both NR5A2 rs3790843 and rs3790844 polymorphism were associated with significantly better prognosis among the female patients group and tumor size >5 cm group in a dominant model." (PMID 25514243, 2014). "Additionally, in the stratified analysis, both NR5A2 rs3790843 and rs3790844 polymorphism were associated with significantly lower risk of death in the groups of female, tumor size >5 cm in a dominant model." (PMID 25514243, 2014). "Our results represent the first demonstration that the NR5A2 rs3790844 polymorphism is associated with increased OS of GC patients in the dominant model, and similar results were found among the female group and tumor size >5 cm group for NR5A2 rs3790843 polymorphism." (PMID 25514243, 2014). "In pancreatic cancer (PC), the autocrine GDF15-GFRAL axis drives tumor growth and metastasis, promoting progression and therapeutic resistance through pathways involving nuclear receptor NR5A2 and p38 MAPK." (PMID 40868185, 2025). "A significant proportion of CRC tumors demonstrated responsiveness to NR5A2 inhibition, particularly when combined with tumor-debulking chemotherapy." (PMID 41214698, 2025). "Their study also revealed a role for NR5A2 in nerve‐related malignant tumors, and that the growth of this type of tumor was significantly inhibited by the use of an agonist for NR5A2." (PMID 38358044, 2024). "In our study, NR5A2 was highly expressed in poorly differentiated tumor tissues than in the well‐differentiated." (PMID 38358044, 2024). "Many studies have shown that NR5A2 plays a critical role in the progression of multiple tumor types." (PMID 38358044, 2024). "Several studies have shown that interference with the NR5A2‐mediated Wnt/β‐catenin pathway using pharmacological agents or via gene regulation can significantly inhibit tumor proliferation, migration, and invasion." (PMID 38358044, 2024). "The potential of circulating tumor cells as non-invasive biomarkers for assessing NR5A2 and SOX2 expression should be explored." (PMID 38012687, 2023). "In the inflammation phase, LRH‐1/Nr5A2‐regulated and Cyp11b1‐mediated intestinal glucocorticoid synthesis prevents tumour development and growth." (PMID 36861295, 2023). "MiR-186 is commonly overexpressed in PDAC, while targeting Nuclear Receptor Subfamily 5 Group A Member 2 (NR5A2) significantly influences tumor cell proliferation and dissemination, which are notably promoted." (PMID 36292753, 2022). "Flow cytometry result exhibited that overexpression of microRNA‐433‐3p notably reverses inhibition of NR5A2 on cell apoptosis (p < 0.05), increases tumor cells in G0/G1 phase, delays cell cycle progression, and inhibits cell proliferation (p < 0.05)." (PMID 36303447, 2022). "We conclude that NR5A2 is an indicator of poor clinical outcomes in ER(+)/ER(−) tumor (1 : 1 ratio) cohort and its ER(−) subcohort." (PMID 26366408, 2015).
tumor (continued). "Considering that miR-139-5p regulation of NR5A2 both in tumor tissues and in adjacent normal tissues operate under the same mechanism, the correlation of miR-139-5p and NR5A2 expression in tumor tissues would be similar to that in adjacent normal tissues." (PMID 24204738, 2013). "Cyclin E1 and MMP9 expression levels were reduced, indicating that these two downstream genes are regulated by NR5A2 and are suggested to participate in neoplasm proliferation and invasive process induced by miR-139-5p, respectively." (PMID 24204738, 2013). "Tumour-derived prostaglandin E2 stimulates the expression of orphan nuclear receptor LRH-1/NR5A2 and increases its occupancy on the nuclear receptor half-site upstream of promoter II." (PMID 19445691, 2009). "Importantly, Cmp3 monotherapy conferred minimal tumor control, reinforcing the concept that NR5A2 inhibition alone is insufficient to fully eradicate CSC populations." (PMID 41214698, 2025). "Circulating tumor cells warrant assessment as non-invasive biomarkers for NR5A2/NANOG expression." (PMID 41214698, 2025). "In summary, these findings suggest that the inhibition of NR5A2 may be an effective strategy for slowing down the development as well as progression of many tumor types." (PMID 38358044, 2024). "In contrast, tumor-suppressive functions have also been ascribed to NR5A2." (PMID 34277436, 2021). "As PTEN is a tumor suppressor, we hypothesized that Nr5a2 depletion would further be manifest in the expression of genes associated with proliferative quiescence." (PMID 33441767, 2021). "NR5A2 promotes tumor growth and metastasis by activating Wnt/beta-catenin signaling." (PMID 33850096, 2021). "Furthermore, heterozygous mutations in NR5A2 rendered the mouse pancreas more susceptible to tissue damage, inhibited tissue regeneration, and cooperated with the mutant KRAS to promote tumor progression." (PMID 34277436, 2021). "The prognostic value of NR5A2 is established by identifying the most relevant prognostic indicators regulated by NR5A2, which are expressed in both ER(−) (91A cohort) and ER(+)/ER(−) (181A cohort) tumor cells." (PMID 26366408, 2015). "Thus, all samples from tumor tissues and adjacent normal tissues were mixed to calculate the correlation coefficient of miR-139-5p and NR5A2." (PMID 24204738, 2013). "Liver receptor homolog 1 (LRH1), also known as nuclear receptor subfamily 5 group A member 2 NR5A2, participates in various biological processes, such as liver and pancreas differentiation, steroidogenesis in childhood, cholesterol/bile acid homeostasis, and tumor progression." (PMID 33194722, 2020). "Thus, NR5A2 is likely to be an oncogene and reduction of NR5A2-antagonists may produce anti-tumor effects." (PMID 26894976, 2016). "Compared with normal controls, the relative mRNA expression levels of NOX4, SCD, and TIMP1 were significantly higher in tumor tissues, while those of AQP8 and NR5A2 were significantly lower." (PMID 41438584, 2026). "Pharmacological inhibition of NR5A2 using Cmp3 significantly sensitized a subset of CRC PDX models to standard chemotherapy, resulting in enhanced tumor regression." (PMID 41214698, 2025). "Nuclear receptor subfamily 5 group a member 2 (NR5A2, known as LRH-1), an orphan nuclear receptor involved in cell development, migration, and metabolism, has been described to help tumor progression and chemotherapy resistance." (PMID 36289931, 2022).
tumor (continued). "A study found that miR-139-5p has the tumor-suppressive features, invasiveness, and growth suppressing characteristic in human ESCC by targeting the 3′ UTR of oncogenic NR5A2." (PMID 32662828, 2020). "Some of them are considered as the tumor suppressor genes of PC, such as PLA2G1B, SERPINI2 and NR5A2." (PMID 31706267, 2019). "The combination of Cmp3—a highly selective pharmacologic inhibitor of NR5A2—with standard-of-care chemotherapy exhibited robust synergistic antitumor efficacy, resulting in enhanced CSC depletion, durable tumor regression, and prolonged survival in preclinical CRC models." (PMID 41214698, 2025). "In SCC-9 cells, NR5A2 silencing downregulated the expression of MET, which is reported to be the downstream target gene of HK2 and responsible for HK2 induced tumor initiation and progression." (PMID 34277436, 2021). "Next, we examined the effects of the silencing of NR5A2 and GDF15 on tumor growth in vivo." (PMID 33850096, 2021). "This is not a consequence of the frequent copy number gain of NR5A2 in ER-positive tumours, as copy number and mRNA expression are not positively correlated in TCGA data (Pearson r=-0.093)." (PMID 29137369, 2017). "In our study, the ability of pulsatile low pH exposure, simulating reflux events, to up-regulate the expression of NR5A2 and GATA6 is suggestive of their role in the mechanism promoting metaplasia and neoplasia in conjunction with epigenetic and polymorphic variation." (PMID 27586588, 2016). "Furthermore, expression of NR5A2 mRNA in ER-negative tumours is strongly correlated with expression of multiple co-regulators and upregulation of ER-related genes, relationships which are not observed in ER-positive tumours." (PMID 29137369, 2017). "The molecular etiology of EC and the pathogenic role of the demonstrated here overexpression of MYC, NR5A2, SNAI1, and TWIST1 in tumor-adjacent tissues is not clear." (PMID 36140779, 2022). "High levels of NR5A2 mRNA in ER-positive tumours may be related to the role of LRH-1 in the ER transcriptional program, but high levels of NR5A2 mRNA do not necessarily lead to high levels of LRH-1 protein or LRH-1 activity." (PMID 29137369, 2017).
inflammation (1 paper, 2019). Aberrant reaction of the microcirculation characterized by movement of fluid and leukocytes from the blood into extravascular tissues. "Moreover, in CAE-induced pancreatic inflammation, Nr5a2 silencing increased the apoptosis and necrosis of acinar cells and inhibited the proliferation of acinar cells, which has not been shown previously." (PMID 31992986, 2019).
NR5A2 also shares sentences with these, for which no sentence is quoted: gastric adenocarcinoma (3 papers); liver cancer (3); Obesity (3); type 1 diabetes mellitus (3); Crohn disease (2); infection (2); invasive breast carcinoma (2); non-small cell lung carcinoma (2); adenoma (1); adrenal hypoplasia (1); Allergy (1); autism (1); bacterial infection (1); brain cancer (1); brain glioma (1); Cachexia (1); cholangiocarcinoma (1); cholestasis (1); colon adenocarcinoma (1); colorectal adenocarcinoma (1); dementia (1); depression (1); Ductal Breast Carcinomas (1); ductal carcinoma in situ (1); epilepsy (1); Glucose intolerance (1); Hepatitis (1); hyperglycaemia (1); inflammatory bowel disease (1); kidney carcinoma (1).
A further 12 diseases each share a sentence with NR5A2 in 1 paper.